EZH2 (enhancer of zeste 2 polycomb repressive complex 2 subunit)
Diseases named in the same sentence as EZH2 in open-access papers (continued):
Sharing a sentence is not in itself a finding about the gene and the disease.
tumor (continued). "A previous study has shown that inhibition of Ezh2 methyltransferase activity can inhibit tumor cells in an Arid1a-mutated model, highlighting the antagonism of Ezh2 and Arid1a in tumor formation." (PMID 31259687, 2019). "EZH2 mutations and expression changes have been described which suggest EZH2 has either proto-oncogenic activity or tumor suppressor activity in different cancer contexts." (PMID 31086012, 2019). "Non-tumor bearing mice with conditional EZH2 loss in hematopoietic stem and progenitor cells or those treated with EZH2 inhibitors show enhanced cell lineage commitment, survival and number of mature NK cells." (PMID 30692641, 2019). "The promotion of subcutaneous tumour growth caused by LINC01535 overexpression was reversed by miR‐214 overexpression or EZH2 silencing." (PMID 31273925, 2019). "Another promising therapeutic concept is the inhibition of ‘enhancer of zeste homolog 2’ (EZH2) in the loss of function of tumor suppressors or amplification of (proto-) oncogenes." (PMID 31108964, 2019). "EZH2 is an important factor associated with aggressive tumor behavior, advanced stage, and poor survival in NSCLC." (PMID 31042721, 2019). "EZH2 usually mediates the methylation of the second lysine of histone H3 and is associated with tumor progression, angiogenesis, inflammation." (PMID 31921641, 2019). "In these tumor entities, a high EZH2 expression has been linked to advanced disease and worse prognosis." (PMID 31317325, 2019). "Pathogenic EZH2 modulates lymphoid oncogenesis by epigenetic repression of tumor suppressors, orchestrating with lncRNAs, site-specific PTMs, affecting microenvironment and EBV-host interplay." (PMID 31752930, 2019). "Further exploration is necessary for the mechanism underlying Ezh2 overexpression in GC, particularly the molecule(s) to which it binds when modulating tumor cell behavior." (PMID 29335012, 2018). "Surprisingly, the functional EZH2 activation (H3k27Me3 overexpression) and EZh2 protein (over expression) cause significant small tumor as compared to control." (PMID 29460395, 2018). "Hernando and colleagues showed that treatment of MM cell lines with EZH2 inhibitor E7438 caused decreased proliferation and increased adherence of tumor cells." (PMID 30555699, 2018). "To test if EZH2 inhibition enhanced the effect of olaparib in primary BRCA-deficient tumor cells, we treated Lin−CD34+ cells from patients with BRCA-deficient AML and from healthy donors with olaparib with or without UNC1999." (PMID 29535829, 2018). "In another study, curcumin was associated with reduced expression of EZH2 and upregulation of a panel of tumor-suppressive microRNAs, such as let-7a,b,c,d, miR-26a, miR-101, miR-146a, and miR-200b,c that are normally absent in pancreatic carcinomas." (PMID 30627525, 2018). "In vivo tumor models, inactivation of EZH2 blocked tumorigenesis driven by SMARCB1 loss, completely." (PMID 29625594, 2018). "The functional analysis uncovered a significant number of differentially regulated genes in Ezh2 knock-out tumours that were associated with cellular differentiation and axonal guidance." (PMID 29959321, 2018). "Recently Ezh2 protein has been disclosed overexpressed and is associated with several tumor proliferation and invasion-associated genes, as well as the prognosis of GC." (PMID 29335012, 2018). "ARMC12 physically binds to RBBP4 to increase the PRC2 complex formation and EZH2 activity, leading to repressed gene expression of downstream tumor suppressive targets associated with NB progression." (PMID 30026490, 2018). "Enhancer of Zeste homologue 2 (EZH2) overexpression is associated with tumor proliferation, metastasis, and poor prognosis." (PMID 30469511, 2018). "EZH2 inhibition was associated with upregulation of microRNAs with potential tumor suppressor functions." (PMID 30285865, 2018).
tumor (continued). "To this end, we performed transcription factor motif enrichment analysis of the subset of genes with elevated expression in Ezh2-null tumours that also underwent loss of H3K27me3 from their promoter regions." (PMID 29959321, 2018). "Overall EZH2 gain in and loss of function studies in in‐vivo xenograft tumor models clearly indicate that EZH2 regulates tumor initiating capabilities and alters metastatic landscape of solid tumors." (PMID 29460395, 2018). "EZH2 encodes the catalytic component of the polycomb repressive complex 2, which acts as a tumor suppressor and is characterized by recurrent loss-of-function mutations in myeloid malignancies." (PMID 30194306, 2018). "EZH2’s identity as oncogene has attracted intense interest, with its aberrant expression levels (mostly elevated) intrinsically associated with tumor progression and poor prognosis." (PMID 29156711, 2017). "The histone methyltransferase EZH2 plays a role in maintenance of the stem component of cancer, and its overexpression and/or mutation typically drives tumor aggressiveness, drug resistance and patients’ poor prognosis." (PMID 28978137, 2017). "EZH2 is increasingly recognized as a target for the treatment of various neoplastic diseases, especially those with RAS-mutations." (PMID 28914765, 2017). "EZH2 has been reported to be overexpressed in many types of cancer, and high levels of EZH2 are associated with tumor aggressiveness." (PMID 28418882, 2017). "The results suggested that the expression level of ALDH1 is associated with tumor stage, lymphovascular invasion and extraprostatic extension, whereas that of EZH2 was correlated with the Gleason score and lymph node metastasis." (PMID 28415635, 2017). "Overexpression of the transcriptional repressor EZH2 is implicated in tumorigenesis and correlates with poor prognosis in several tumour types." (PMID 28445158, 2017). "We here demonstrate that the observed downregulation of MM-associated oncogenes upon EZH2 inhibition correlates with upregulation of miRNA with tumor suppressor function; mainly miR-125a-3p, miR-320c." (PMID 28052011, 2017). "The oncogenic function of EZH2-catalyzed methylation is known to rely on transcriptional silencing of tumor-associated genes." (PMID 28418882, 2017). "Previous reports have demonstrated that in PBC, EZH2 expression was significantly increased in malignant tumors, and was associated with a larger tumor size, ER- and PR-negative status, TNBC, advanced stage disease and reduced progression-free survival and OS." (PMID 28241804, 2017). "We show that EZH2 inhibition reactivates the expression of microRNAs with tumor suppressor functions predicted to target MM-associated oncogenes; primarily miR-125a-3p and miR-320c." (PMID 28052011, 2017). "In contrast, the proliferation-independent expression of EZH2 displays an inverse association with tumor outcome, with low EZH2 expression being linked to poor prognosis." (PMID 28758948, 2017). "In CCA patients, EZH2 overexpression is associated with tumor stage, lymph node positivity, and poor prognosis." (PMID 28122578, 2017). "EZH2 is associated with histone methyltransferase activity, and its expression is correlated with tumor aggressiveness, metastasis, and poor prognosis." (PMID 29657263, 2016). "The fusion protein EWS-FLI1 in Ewing's sarcoma cells promotes the expression of EZH2 and has been associated with endothelial/neuroectodermal differentiation in this type of tumor." (PMID 27793053, 2016). "Different mechanisms were reported as cause of increased EZH2-dependent signaling in tumor cells, like gene mutations, amplification, certain transcriptional signals and pathways, hypoxia, and multiple microRNAs." (PMID 27222667, 2016).
tumor (continued). "Converging lines of investigation have implicated that EZH2 is likely to be an important mediator of tumor cell plasticity and involves in development and progression of serval cancers." (PMID 27835578, 2016). "In another AML murine model, Ezh2 loss inhibits cancer cell proliferative capacity and disrupts tumor progression by re-activating EZH2 target genes that are implicated in myeloid cell differentiation." (PMID 26497210, 2016). "Overexpression of EZH2 was associated with tumor malignancy and a poor prognosis in human cancers including nasopharyngeal esophageal, breast, gastric, hepatic, pancreatic, ovarian, and bladder cancers." (PMID 27049834, 2016). "Previously, we had shown that EZH2 expression in ≥ 1% of tumor cells was associated with high GS and biochemical recurrence." (PMID 27191985, 2016). "EZH2 expression is associated with increased tumor cell proliferation and regulates cell invasion mostly through mediating transcriptional silencing of tumor suppressor genes like E-cadherin." (PMID 27608009, 2016). "One patient, evaluated for EZH2 status, possessed a specific EZH2 tumor mutation (histidine instead of tyrosine 646, Y646H)." (PMID 27222667, 2016). "EZH2 activity has been linked with oncogenesis where it is thought to block expression of certain tumor suppressors." (PMID 27764181, 2016). "EZH2 mRNA transcript and protein levels are consistently elevated in HCC in comparison with non-tumor liver tissues, and high levels of EZH2 are associated with HCC invasion and metastasis and poor prognosis." (PMID 27239288, 2016). "Down-regulation of these circadian genes is likely to be caused by several non-genetic factors, including promoter methylation, overexpression of EZH2 or other factors, which is tightly associated with the disturbance of cell cycle, tumor size and tumor grade." (PMID 26843619, 2016). "Knockdown of human EZH2 in T cells elicited poor anti-tumor immunity, whereas EZH2+CD8+ T cells were associated with improved survival in patients." (PMID 27784285, 2016). "MiR-101 is a tumor suppressive miRNA that is commonly lost during PCa progression and it is associated with over-expression of its target gene, EZH2." (PMID 27683042, 2016). "EZH2 mutations have been found in various malignancies, while EZH2 expression levels are associated with the prognosis of human neoplasms suggesting the potential involvement of EZH2 in the development and progression of cancer." (PMID 27793053, 2016). "EZH2 expression was previously evaluated in breast carcinomas and was reported to be significantly associated with increased tumor cell proliferation and as a marker of aggressive behavior." (PMID 27113214, 2016). "EZH2 overexpression is also associated with metastasis, tumor progression, and poor clinical outcome." (PMID 27222667, 2016). "And examination of HNSCC specimens showed EZH2 expression was associated with tumor size, histological differentiation and clinical stage." (PMID 26378043, 2015). "The over-activation or over-expression of EZH2 has been linked to aberrant repression of some tumor suppressor genes, and is often implicated in tumor progression and correlates with poor prognosis." (PMID 25923513, 2015). "EZH2 is associated with tumor cell proliferation in PA and its specific inhibitor GSK126 is able to affect tumor cell viability and proliferation in vitro." (PMID 26593398, 2015). "Spearman correlation analysis validated further a significant positive association between levels of Top2a and Ezh2 mRNA levels in 2 independent human primary tumor datasets." (PMID 25605014, 2015). "EZH2 overexpression is implicated in tumorigenesis and correlates to poor prognosis in several tumour types." (PMID 26268310, 2015). "The malignant rhaddoid tumor G401 cells harbor homozygous inactivating mutations in SMARCB1/INI1 that render them depend on WT EZH2 activity for survival." (PMID 26360609, 2015).
tumor (continued). "A recent study demonstrated that EZH2 silencing in tumor-associated endothelial cells inhibited angiogenesis via the reactivation of VASH1." (PMID 26452129, 2015). "In these tumor types, high levels of EZH2 are associated with advanced stages of cancer and poor prognosis." (PMID 26637281, 2015). "In most cancer types, elevated EZH2 function has predominantly been associated with tumor cell proliferation, cell cycle and migration." (PMID 26378043, 2015). "Higher levels of NBAT1 in low-risk tumours enable its interaction with EZH2 and subsequent recruitment to the NBAT1 target gene promoters." (PMID 26087192, 2015). "Analysis of The Cancer Genome Atlas (TCGA) HNSCC data indicated that EZH2 over-expression was associated with high tumor grade and conferred poor prognosis." (PMID 26378043, 2015). "Positive staining for EZH2 was localized in the nuclei of tumor cells and cancer-associated fibroblasts (CAF)." (PMID 25025074, 2014). "Increased expression of EZH2 in HCC has been documented in many studies; our study found that EZH2 expression was closely associated with tumor differentiation and vascular infiltration." (PMID 25226601, 2014). "The tumor cells and cancer associated fibroblasts in the metastatic foci had the highest staining index of EZH2 staining." (PMID 25025074, 2014). "EZH2, an important gene in cell cycle regulation, was associated with an aggressive tumour phenotype, with high levels of EZH2 correlating with reduced 5-year survival (EZH2-negative 71% patients disease free; EZH2-positive, only 48%)." (PMID 27429260, 2014). "Overexpression of EZH2 has been detected in diverse cancers, and is associated with tumor malignancy." (PMID 25520914, 2014). "Mounting evidence shows that overexpression/amplification or mutations of EZH2 have been detected in a variety of cancers, and are associated with tumor development and progression." (PMID 25520914, 2014). "All these data provided strong evidence that high expression of EZH2 was closely associated with tumor angiogenesis in NPC." (PMID 25237831, 2014). "EZH2 over activity, which results in epigenetic gene-silencing, has been associated with many tumour properties including invasion, angiogenesis and metastasis but little is known about the underneath molecular mechanisms." (PMID 25549357, 2014). "EZH2 is a tumor promoter and is found over-expressed or mutated in many solid tumors and hematological malignancies." (PMID 25255445, 2014). "The methylation of H3K27 mediated by EZH2 has been implicated in the aggressive phenotype of cancer cells through the repression of a panel of tumor suppressor genes." (PMID 24093096, 2013). "EZH2 is a histone methyl transferase that is highly expressed in several cancers and associated with tumor cell proliferation, invasion, and metastasis." (PMID 24490161, 2013). "Our study and previous reports have demonstrated that tumor specimens are heterozygous for the Y646 EZH2 mutations." (PMID 23361872, 2013). "Assessing tumor burden via non-invasive, quantitative bioluminescent imaging, we observed a striking loss of tumorigenicity in EZH2-KD compared to control cells." (PMID 23826629, 2013). "Overexpression of EZH2 has been observed in multiple tumor types, and associated with poor prognosis." (PMID 23300840, 2012). "Elevated EZH2 immunoreactivity in the tumor was associated with adverse clinical outcome in what appears to be predominantly oriental NSCLC patient cohorts." (PMID 23300840, 2012). "Our findings demonstrated a further up-regulation of EZH2 in lymph node metastasis relative to primary tumor, and its positive association with tumor proliferation, suggesting a pivotal role of EZH2 in the lymph node metastatic process." (PMID 23251464, 2012). "Given that EZH2 has been associated with tumor cell proliferation, the proliferation marker Ki67 was included in the staining to investigate the correlation of EZH2 with tumor cell proliferation." (PMID 23251464, 2012).
tumor (continued). "Even in the monophasic and biphasic subtypes, higher expression of EZH2 was associated with higher proliferation rate, larger tumor size, and the risk of developing distant metastasis." (PMID 23110793, 2012). "Nevertheless, high EZH2 score also proved to be a valuable predictor of disease outcome, since it was significantly associated with larger tumor size and the presence of distant metastasis." (PMID 23110793, 2012). "High expression of EZH2 is generally associated with advanced stages of tumor progression, aggressive tumor behavior, and dismal clinical outcome." (PMID 23110793, 2012). "We found that miR-26a is aberrantly downregulated in RMS cell lines and primary tumors as compared to non-tumor counterparts, and that miR-26a loss of expression is paralleled by an overexpression of EZH2." (PMID 21609503, 2011). "These analyses revealed that >25-50% nuclear EZH2 expression in the tumor significantly correlated with an increased risk of cancer specific death in patients suffering from non-metastasized RCC (HR 2.72, p = 0.025)." (PMID 20920340, 2010). "Recently, deep sequencing analysis discovered mutated and consequently inactive EZH2, identifying EZH2 as a tumor suppressor gene in difffuse large B-cell lymphoma." (PMID 20565746, 2010). "Recently, an increasing number of studies linked various oncogenic properties to EZH2, including impaired cellular differentiation and enhanced proliferation and in vivo tumor growth." (PMID 21321380, 2010). "Enhancer of Zeste Homolg 2 (EZH2) expression is regulated by RUNX1, STAT3 and E2F3 and high expression of EZH2 gene is associated with the tumor death and also correlated to the pathological stage." (PMID 20025723, 2009). "There was a significant association between a high EZH2 index and increased tumour cell proliferation, as assessed by Ki-67 expression (P<0.001)." (PMID 19773751, 2009). "In these malignancies, EZH2 expression in tumour cells was linked to an aggressive clinical behaviour and worse prognosis." (PMID 19773751, 2009). "We and others have already observed that EZH2 overexpression is linked to aggressive tumours with a high proliferation rate and a poor prognosis." (PMID 19709408, 2009). "To obtain further insight into the differential associations of BMI1 and EZH2 with overall survival, we analysed the mRNA expression levels of these PcG genes in tumours ranked according to grade." (PMID 19099573, 2008). "Enhancer of Zeste Homolog 2 (EZH2)-mediated epigenetic repression has been implicated in immune evasion, yet the contribution of EZH2-repressed genes to anti-tumor immunity and clinical outcomes in TNBC remains unclear." (PMID 42192966, 2026). "Similarly, upregulated Urothelial Cancer Associated 1 (UCA1) was also observed to be increased after HBx in HBV-associated HCC, and promotes tumor growth and metastasis via recruiting EZH2 and repressing p27Kip1/CDK2 signaling in patients with chronic HBV." (PMID 40625740, 2025). "Moreover, the immunosuppressive TME is supported by Tregs and tumor-associated macrophages (TAMs), whose differentiation is also promoted by epigenetic enzymes such as EZH2 and DNMTs." (PMID 40868849, 2025). "Mutations or overexpression of EZH2 are linked to various cancers, as EZH2-mediated changes in H3K27me3 lead to chromatin compaction and transcriptional silencing, contributing to inflammation and tumor progression." (PMID 40042761, 2025). "EZH2 can be directly mutated or it can be impacted by other mutations that either disrupt or enhance its function, and it can function as either a tumor suppressor or oncogene, depending on the context." (PMID 40791365, 2025). "Enhancer of zeste homolog 2 (EZH2) is a key epigenetic regulator implicated in tumor progression." (PMID 41156200, 2025). "Functional studies illustrate that loss of KDM6A or KMT2D promotes tumor growth and may sensitize cells to specific targeted therapies such as EZH2 inhibitors." (PMID 41373802, 2025).